AR (androgen receptor)
Diseases named in the same sentence as AR in open-access papers (continued):
Sharing a sentence is not in itself a finding about the gene and the disease.
prostate carcinoma (continued). "Because androgen receptor (AR) plays a critical role in the proliferation and migration of prostate cancer (PCa) cells, the vast majority of patients with hormone sensitive PCa (HSPC) respond to androgen-deprivation therapy (ADT)." (PMID 34885125, 2021). "Experiments have shown correlation between PCGEM1 and AR3, a principal and clinically important alternatively spliced form of AR in prostate cancer." (PMID 34831421, 2021). "Another study has identified a feed-forward regulatory circuit between AR and PlncRNA-1, which enhances progression of prostate cancer." (PMID 34831421, 2021). "Metformin induces SMILE in prostate cancer cells, thus suppressing the function of the androgen receptor." (PMID 34211461, 2021). "This acquired knowledge was fundamental in developing AR target therapy and medicines for prostate cancer patients." (PMID 34440475, 2021). "In our previous researches, we have been explored the effect of USP14 on the growth of prostate cancer and breast cancer cells via regulating the stability of AR." (PMID 34548474, 2021). "We have previously shown that PIM1 phosphorylates the androgen receptor (AR), the primary therapeutic target in prostate cancer, at serine 213 (pS213), which alters expression of select AR target genes." (PMID 34697370, 2021). "Most treatment-naïve prostate cancers (PCa) depend on androgen receptor (AR) signaling to proliferate." (PMID 34884545, 2021). "On the other hand, a handful of miRNAs have been found to exert oncogenic roles in prostate cancer, through the regulation of transcription of AR expression or signaling." (PMID 34831421, 2021). "Enzalutamide (ENZ) is a second-generation androgen receptor antagonist employed for treatment of metastatic castration-resistant prostate cancer A considerable proportion of tumors eventually develop resistance during treatment." (PMID 34776951, 2021). "In a focused screen using an shRNA library silencing spliceosome-related genes, ATP-dependent RNA helicases 39A and 39B (DDX39A and DDX39B) were found to be involved in the splicing of the androgen receptor (AR) in prostate cancer." (PMID 34065983, 2021). "Prostate cancer tissues also express androgen receptor (AR) and utilize circulating testosterone for growth and development." (PMID 33418978, 2021). "It suggests that some downstream regulatory factors in the AKT and AR interaction network play a vital role in prostate cancer metastasis and are potential targeting molecules for prostate cancer metastasis treatment." (PMID 33377281, 2021). "The androgen receptor (AR) is the main driving force behind the growth and progression of prostate cancer (PC), the most common carcinoma in men." (PMID 34575023, 2021). "Manipulating the AR signalling axis is the focus for prostate cancer therapy; thus, it is crucial to understand the role of androgens and AR on extracellular vesicle (EV) secretion and cargo." (PMID 34434533, 2021). "Co-immunoprecipitation assays have confirmed a direct interaction between AR and HIF1α, and ChIP analysis showed HIF1α interacts with the AR in genes involved in prostate cancer." (PMID 33784295, 2021). "Resistance to drugs targeting the androgen receptor (AR) signaling axis remains an important challenge in the treatment of prostate cancer patients." (PMID 34211036, 2021). "Downregulation of miR-27a caused by aberrant AR signalling and PI3K/Akt signalling after ADT was proposed to promote the progression of castration-resistant prostate cancer." (PMID 34940756, 2021). "Enzalutamide, an AR antagonist that is commonly used in the treatment of prostate cancer, has also shown antitumor effects in TNBC because 30% of TNBC patients demonstrate AR‐positive disease." (PMID 34977868, 2021). "In line with a function in driving disease progression and dedifferentiation towards the loss of AR expression, we demonstrate how EZH2 inhibition reverts the transcriptional output of prostate cancer cells along the progression trajectory." (PMID 34857732, 2021).
prostate carcinoma (continued). "Other studies have shown that GSK-J4 treatment inhibited proliferation of castration-resistant prostate cancer cells by inhibiting AR–driven transcription and can also inhibit proliferation in glioma cells in a dose-dependent manner in vitro." (PMID 34220955, 2021). "In prostate cancer, we found that AR drives formation of a shortened EWSR1 isoform that promotes cancer-associated phenotypes." (PMID 34409300, 2021). "The ability of AR to repress transcription in LNCaP prostate cancer cells is related among other factors to cooperation with EZH2 histone-modifying enzyme, a component of the polycomb repressor complex 2 (PRC2)." (PMID 33430890, 2021). "Epigenomic and transcriptomic profiling of 4 clonal metastatic samples taken from a patient with prostate cancer during a single autopsy reveals sample‐shared/specific Androgen Receptor (AR) binding sites with enhancer activity." (PMID 33576154, 2021). "AR45 was previously found to be widely expressed in human tissues to interact with AR in two-hybrid assays and inhibit proliferation when overexpressed in prostate cancer LNCaP (Lymph Node Carcinoma of the prostate) cells." (PMID 34417184, 2021). "In particular, estrogen (ER) and androgen receptors (AR) drive the development and progression of breast and prostate cancer, respectively." (PMID 34137734, 2021). "pS81 is co‐stimulated by CDK1 and CDK9, both representing potential therapeutic targets in castration‐resistant prostate cancer patients, either alone or in conjunction with direct AR antagonists." (PMID 33932081, 2021). "Androgen receptor (AR) is an essential molecule in prostate cancer (PCa) development and the major target in PCa therapy." (PMID 33932081, 2021). "In particular, the ETS family member ELK1 was found to interact with the N-terminal domain (NTD) of AR and directly regulate its recruitment to chromatin in prostate cancer cells." (PMID 33513133, 2021). "The lasso results also showed that five genes (AR, PDHA1, RAN, DPP4 and DAZAP1) were the powerful composed factors of prostate cancer risk prediction model." (PMID 33407865, 2021). "For instance, enzalutamide is a successful FDA-approved drug that targets castration-resistant prostate cancer via androgen receptor antagonism; however, inevitably resistance occurs." (PMID 33839157, 2021). "BRCA1 coregulates the androgen receptor (AR) which mediates a signalling pathway crucial in developing prostate cancer." (PMID 34884434, 2021). "Cholestane-3β-5α-6β-triol was shown to suppress the proliferation of human prostate cancer cells such as LNCaP CDXR-3 (androgen receptor-positive) and DU-145 and PC-3 (both androgen receptor-negative)." (PMID 34571949, 2021). "The IC50 of enzalutamide in cell viability assays for VcaP, an AR dependent prostate cancer cell line, is 410 nM." (PMID 34094902, 2021). "PirH2 is also related to the development of prostate cancer as it interacts with the AR as well as with one of the AR repressors, HDAC1." (PMID 34577077, 2021). "The androgen receptor (AR) signaling pathway plays an important role in the initiation and progression of prostate cancer." (PMID 34685466, 2021). "Endocrine therapy for prostate cancer (PCa) mainly inhibits androgen receptor (AR) signaling, due to increased androgen synthesis and AR changes, PCa evolved into castration-resistant prostate cancer (CRPC)." (PMID 34215720, 2021). "MED1 is overexpressed in prostate cancer cells where it acts as an essential coactivator for AR-mediated transcription, and its knockdown results in cell-cycle arrest, decreased proliferation, and increased cell death." (PMID 33384381, 2021). "Over the last few decades, many researchers have pursued endeavors to re-activate AR expression in progressed prostate cancer cells." (PMID 33420371, 2021). "Androgen Receptor (AR), a steroid receptor TF for testosterone and di-hydrotestosterone, played a critical role in prostate cancer, especially in the castration resistant sub-type." (PMID 34062779, 2021).
prostate carcinoma (continued). "We and others have previously shown that PIM1 phosphorylates AR, the primary therapeutic target in prostate cancer, at S213, affecting the expression of select AR target genes." (PMID 34697370, 2021). "Nevertheless, p38 MAPK inhibition represents a strategy to inhibit the proliferation and survival of AR-dependent prostate cancer cells in vitro and in vivo, including those representing CRPC." (PMID 33671134, 2021). "An important area of research in prostate cancer is the interaction between signaling pathways of IL-6 and AR." (PMID 34204596, 2021). "MiRNAs play a relevant role in PC (prostate cancer) by the regulation in the expression of several pathways’ AR (androgen receptor), cellular cycle, apoptosis, MET (mesenchymal epithelium transition), or metastasis." (PMID 34198846, 2021). "In prostate cancer, androgens—through activation of their receptor AR—have also been shown to be major orchestrators of specific metabolic pathways, such as mitochondrial respiration, lipid synthesis and usage, and glycolysis modulation." (PMID 34456857, 2021). "Androgen and androgen receptor (AR) play an important role in the growth of the prostate, the maintenance of efficacy, and the occurrence and progression of prostate cancer." (PMID 34124242, 2021). "YAP/TAZ signaling is a positive regulator of AR signaling, and it is suggested to be responsible for CR in prostate cancer." (PMID 33807895, 2021). "In contrast, the addition of IL-6 or transiently transfected with an overexpression plasmid for AR significantly restored prostate cancer cell proliferation and colony formation, which was reduced by knockdown of IRE1α in C4-2B cells." (PMID 34295814, 2021). "Although the introduction of multiple agents that potently target the AR signaling axis (including abiraterone, enzalutamide and apalutamide) has improved outcomes for men with advanced prostate cancer, primary and acquired resistance remains common." (PMID 35008216, 2021). "The antiproliferative potency of 5,7,20-O-trimethylsilybin and its nine 3-carbamoyl derivatives were assessed in an AR-positive LNCaP prostate cancer cell line and two AR-null prostate cancer cell lines (PC-3 and DU145)." (PMID 34770829, 2021). "AR antagonists have been used to treat prostate cancer for more than 35 years with extensive clinical experience and accumulation of biological data." (PMID 34094902, 2021). "As activation of the androgen receptor by androgens represents a key lineage specific oncogenic pathway in prostate cancer, androgen deprivation/antagonization therapies (ADT) remain the uniform treatment modality up to this very day." (PMID 33531470, 2021). "Prostate cancer is induced by the translocation of complex made by androgen receptor (AR) and his ligand [e.g. dihydrotestosterone (DHT) and testosterone, or other androgenic steroids] from the cytoplasm to the nucleus of prostate cells." (PMID 33712665, 2021). "Prostate cancer is critically dependent on activation of the androgen receptor (AR), a ligand-activated transcription factor, for cancer cell growth and survival." (PMID 34322653, 2021). "The androgen receptor (AR) pathway is a key driver in prostate tumorigenesis, regulating genes that drive prostate cancer cell proliferation." (PMID 34211036, 2021). "This indicates that p38 MAPK inhibition decreases cell proliferation in prostate cancer cells expressing AR." (PMID 33671134, 2021). "Brooke and others discovered that FUS served as the important process connecting prostate cancer (PCa) cell cycle progression with androgen receptor signal transduction." (PMID 34746238, 2021). "CLNS1A cooperates with the protein PRMT5 and functions as an epigenetic activator of AR transcription in castration resistance prostate cancer." (PMID 34439272, 2021).
prostate carcinoma (continued). "In prostate cancer, some have shown that AR and EGFR proteins are inversely correlated, while others have shown a positive correlation." (PMID 34681618, 2021). "The AR-NTD small molecule inhibitor prototype identified in this work possesses promising clinical utility for treating resistant forms of late-stage prostate cancer." (PMID 34298700, 2021). "The target proteins of E3 ligases in prostate cancer, among others, are the driving proteins, such as AR, ERG, PTEN, cell-cycle progression proteins, and other transcription factors and signaling molecules." (PMID 33572160, 2021). "AR promotes male-specific characteristics and is involved in prostate cancer initiation and progression." (PMID 34409300, 2021). "The complexity of AR-dependent metabolic changes has made it difficult to completely molecular characterise prostate cancer metabolism." (PMID 34262149, 2021). "Around 80–90% of cases of prostate cancers are required to measure androgen at initial diagnosis, and endocrine therapy of prostate cancer is directed toward the reduction of serum androgens and inhibition of AR." (PMID 34805155, 2021). "HOXB13 can also resist tamoxifen-induced apoptosis of cancer cells and can inhibit the growth of prostate cancer cells through the Wnt signal pathway and androgen receptor signal pathway." (PMID 34306077, 2021). "We immobilized GST-Af1521 on glutathione beads, performed pull-down assays with extracts from PC3-AR prostate cancer cells, and examined the bound fractions by AR immunoblotting." (PMID 33976187, 2021). "Androgen receptor in prostate cancer (PCa) transcriptionally represses multiple genes including MYC." (PMID 34911936, 2021). "ELK1 is an ETS transcription factor that controls AR transcriptional activity and promotes prostate cancer progression." (PMID 33513133, 2021). "This inhibitor blocks CBX2-facilitated neuroendocrine differentiation in prostate cancer, mainly through de-repressing AR signaling in neuroendocrine differentiated prostate cancer cells." (PMID 34617019, 2021). "SREBF1 was involved in fatty acid metabolism, and expression of SREBF1 mediated by AR/mTOR complex accelerated metabolism of fatty acid, to meet the demand for prostate cancer cell growth." (PMID 34116604, 2021). "Human prostate cancer cell line LnCap, an AR-positive cell line, was used as a positive control for AR and c-Myc expression in GBM cells." (PMID 34094902, 2021). "In prostate cancer, a known number of alternative AR activation pathways exist, driven by cytokines and growth factors." (PMID 33477370, 2021). "The androgen receptor (AR) signaling pathway plays a vital role in the diagnosis and treatment of prostate cancer." (PMID 34685466, 2021). "Calcitriol can increase AR protein expression in LNCaP prostate cancer cells, while we have previously shown that aPPD significantly inhibited AR protein expression and activities in vivo in the C4-2 xenograft mouse model." (PMID 34199743, 2021). "The most active compounds 17, 23, 25 and 27 were tested in vitro in DU145, an androgen insensitive prostate cancer cell line (PCa) with very low or undetectable AR levels, which represents the castration-resistant PCa (CRPC) model." (PMID 34583596, 2021). "FOXA1 can enable recruitment of ERα and the androgen receptor (AR) to their respective response elements in breast and prostate cancer, respectively." (PMID 34831189, 2021). "For example, in Honda’s study, the authors defined the abundantly expressed tRNA halves in estrogen receptor (ER)-positive breast cancer and androgen receptor (AR)-positive prostate cancer cell lines as Sex Hormone-dependent tRNA-derived RNAs (SHOT-RNAs)." (PMID 34537813, 2021).